GDF6 (growth differentiation factor 6)
Description:
Growth factor that controls proliferation and cellular differentiation in the retina and bone formation. Plays a key role in regulating apoptosis during retinal development. Establishes dorsal-ventral positional information in the retina and controls the formation of the retinotectal map. Required for normal formation of bones and joints in the limbs, skull, digits and axial skeleton. Plays a key role in establishing boundaries between skeletal elements during development. Regulation of GDF6 expression seems to be a mechanism for evolving species-specific changes in skeletal structures. Seems to positively regulate differentiation of chondrogenic tissue through the growth factor receptors subunits BMPR1A, BMPR1B, BMPR2 and ACVR2A, leading to the activation of SMAD1-SMAD5-SMAD8 complex. The regulation of chondrogenic differentiation is inhibited by NOG. Also involved in the induction of adipogenesis from mesenchymal stem cells. This mechanism acts through the growth factor receptors subunits BMPR1A, BMPR2 and ACVR2A and the activation of SMAD1-SMAD5-SMAD8 complex and MAPK14/p38 (By similarity).
Synonyms: BMP-13; BMP13; KFS; KFS1; CDMP2; KFM; KFSL; SGM1; SYNS4
Tractability: Antibody: UniProt places it where antibodies can reach, with high confidence; UniProt predicts a signal peptide or a membrane-spanning region; its Gene Ontology location is reachable by antibodies, with medium confidence.
Gene: Protein-coding gene on chromosome 8 (96,142,333 to 96,160,806, reverse strand). Ensembl gene ENSG00000156466.
Subcellular location: Secreted
Subcellular location (Human Protein Atlas): Vesicles; Nuclear membrane; Nucleoplasm; Predicted to be secreted
Gene Ontology:
Molecular function: cytokine activity; growth factor activity; identical protein binding
Biological process: activin receptor signaling pathway; BMP signaling pathway; metanephros development; positive regulation of chondrocyte differentiation; positive regulation of DNA-templated transcription; positive regulation of SMAD protein signal transduction; apoptotic process; fat cell differentiation; positive regulation of p38MAPK cascade; retinal cell apoptotic process; positive regulation of cell differentiation
Cellular component: extracellular region
Genetic constraint (gnomAD): Loss-of-function variants: 4 observed, 26.78 expected, observed/expected ratio (o/e) 0.15, 90% interval 0.073 to 0.34. The upper end of that interval is the gene's LOEUF score, 0.34, which puts it in group 1 of 6, group 1 being the genes least tolerant of losing a copy. Missense variants: 589 observed, 594.83 expected, observed/expected ratio (o/e) 0.99, 90% interval 0.93 to 1.06. Synonymous variants: 296 observed, 262.9 expected, observed/expected ratio (o/e) 1.13, 90% interval 1.02 to 1.24.
Homologues: Orthologues: chimpanzee GDF6 (99% identical), macaque GDF6 (98% identical), pig GDF6 (94% identical), mouse Gdf6 (88% identical), rabbit GDF6 (87% identical), rat Gdf6 (86% identical), dog GDF6 (71% identical), guinea pig GDF6 (64% identical), tropical clawed frog gdf6 (59% identical). Paralogues in human: GDF5 (45% identical), GDF7 (43% identical), BMP10 (27% identical), BMP4 (25% identical), BMP5 (25% identical), BMP7 (25% identical), GDF2 (25% identical), BMP2 (24% identical), BMP8A (24% identical), BMP8B (24% identical), BMP6 (24% identical), NODAL (21% identical), and 19 more.
Diseases named in the same sentence as GDF6 in open-access papers:
GDF6 is named in the same sentence as 103 diseases in open-access papers, as found by Europe PMC text mining. Sharing a sentence is not in itself a finding about the gene and the disease. The quoted sentences say what the papers report.
microphthalmia (13 papers, 2010 to 2025). Congenital or developmental anomaly in which the eyeballs are abnormally small. "Previously, GDF6 variants were reported to cause pleiotropic defects including skeletal, e.g., vertebral, carpal, tarsal fusions, and ocular, e.g., microphthalmia and coloboma, phenotypes." (PMID 32737436, 2020). "Mutations in the GDF6 gene lead to the Klippel-Feil syndrome, microphthalmia, anophthalmia, and age-related macular degeneration (AMD)." (PMID 27311402, 2016). "Mutations in gdf6 genes have also been linked to other ocular anomalies, including microphthalmia and coloboma." (PMID 26893342, 2016). "A cohort of 200 unrelated probands with coloboma, microphthalmia and/or anophthalmia was screened for mutations in the GDF6 gene." (PMID 21070663, 2010). "Mutation analysis of the GDF6 gene in 200 patients with microphthalmia revealed amino acid substitutions in four of them." (PMID 21070663, 2010). "Our study adds to others linking eye defects to abrogation of Gdf6 function in fish, mice and humans, but the mechanisms connecting loss of gdf6a to microphthalmia have remained unclear." (PMID 26893342, 2016). "Loss of function in homologues of GDF6 induces microphthalmia in zebrafish, mice and humans." (PMID 24681822, 2014). "Disruption of human GDF6 and homologs in mice, Xenopus or zebrafish produces anophthalmia, microphthalmia and coloboma with varying degrees of penetrance and severity." (PMID 24681822, 2014). "Sequence alternations in GDF6, such as amino acid substitutions, have been identified in some patients with ocular anomalies (microphthalmia, anophthalmia, coloboma) and vertebral segmentation anomalies." (PMID 25416513, 2014). "More recently, mutations in three members of the transforming growth factor-β (TGF-β) superfamily (BMP4; GDF6, also known as BMP13; and GDF3) have been associated with microphthalmia/anophthalmia." (PMID 21070663, 2010). "A segmental deletion encompassing the GDF6 gene, and several amino acid substitutions in GDF6 have been identified in patients with ocular anomalies, including coloboma and microphthalmia." (PMID 21070663, 2010). "To investigate the role of GDF6 in human eye defects, we screened the GDF6 gene in 200 patients suffering from microphthalmia, anophthalmia or related abmormalities, and detected amino acid substitutions in four of them." (PMID 21070663, 2010). "GDF6 A249E mutation is also linked to microphthalmia/anophthalmia with and without skeletal abnormalities, hereditary retinal dystrophy, and Chiari type I malformation (displacement of the cerebellar tonsils below the base of the skull)." (PMID 33147457, 2020). "Indeed, variants in GDF6 (BMP13), BMP4, and SMOC1 are linked to inferior coloboma and microphthalmia." (PMID 29522511, 2018). "Amino acid substitutions in GDF6 were detected in 4 (2%) of 200 patients with microphthalmia." (PMID 21070663, 2010). "Amino acid substitutions in GDF6 were detected in four patients with microphthalmia." (PMID 21070663, 2010).
melanoma (12 papers, 2011 to 2025). A malignant, usually aggressive tumor composed of atypical, neoplastic melanocytes. "Complementing the discovery that GDF6-activated BMP signaling suppresses differentiation to promote invasive melanoma, Gramann and colleagues found that loss of the zebrafish ortholog gdf6a in development leads to an excess of melanocytes specified from the neural crest." (PMID 32455885, 2020). "High GDF6 expression predicted improved response in anti-PD-L1 Cohort, derived from melanoma patients treated with Durvalumab + Trametinib (AUC = 0.506)." (PMID 40699648, 2025). "We also note an 8-fold increase in expression of the growth differentiation factor 6 gdf6a, which has been shown to be transcriptionally upregulated in melanoma and is involved in BMP signaling, promoting a neural crest signature and impacting differentiation." (PMID 40719625, 2025). "GDF6 developed a neural crest genetic fingerprint in A375 melanoma cell lines, and upregulated the NC markers SOX10, FOXD3, and SNAI2 while downregulating the growth inhibiting SOX9 protein." (PMID 38426087, 2024). "GDF6 was also linked to low levels of MITF, further demonstrating its ability to manipulate melanoma phenotypes." (PMID 38426087, 2024). "The melanocyte differentiation gene MITF and the proapoptotic factor SOX9 were negatively regulated by GDF6, which blocked melanoma differentiation, inhibited cell death, and promoted tumor growth." (PMID 36253873, 2022). "An extra copy of chromosome 8q, containing the DGAT1 locus but also other putative melanoma oncogenes ASAP1/DDEF, MYC, and GDF6, has been observed in approximately 30% of melanoma cases." (PMID 35732120, 2022). "In MiniCoopR-based screening of genes amplified in both species, the bone morphogenetic protein (BMP) ligand GDF6 (gdf6a and gdf6b in zebrafish) was identified as a new melanoma oncogene." (PMID 32455885, 2020). "Our laboratory recently identified a BMP ligand, GDF6, that acts to suppress differentiation and cell death in melanoma." (PMID 31868592, 2019). "MITF is downregulated by GDF6-activated BMP signaling to prevent melanocytic differentiation in melanomas." (PMID 31868592, 2019). "We found that GDF6-activated BMP signaling in melanoma cells represses expression of MITF, a key regulator of melanocyte differentiation, leading to a less differentiated state." (PMID 31868592, 2019). "Recent identification of the BMP ligand GDF6 as a novel melanoma oncogene showed GDF6-activated BMP signaling suppresses differentiation of melanoma cells." (PMID 31868592, 2019). "Our results support this regulatory role and provide a developmental context in vivo to understand why GDF6-activated BMP signaling is able to regulate MITF in melanoma cells." (PMID 31868592, 2019). "Most recently, it was shown that activation of BMP signaling via the ligand GDF6 governs an embryonic cell gene signature to promote melanoma progression." (PMID 29716947, 2018). "GDF6 protein expression varies markedly across cancer types; melanoma exhibits the highest expression (~90% positive staining), followed by thyroid cancer with moderate expression (~50%), while prostate cancer and carcinoid show lower expression levels (~20–30%)." (PMID 40699648, 2025). "Consistently, DGAT1, ASAP1, MYC, and GDF6 are co-amplified in melanoma and other cancers." (PMID 35732120, 2022). "This hypothesis was driven, in part, by our previous data in human melanoma cells, in which knockdown of GDF6 decreased phospho-SMAD1/5/8 binding at the MITF locus and increased MITF expression." (PMID 31868592, 2019). "Taken together, these findings suggest therapeutic targeting of GDF6 or BMP signaling would likely have a positive impact on prognosis and outcome in melanoma patients by promoting differentiation in tumors." (PMID 31868592, 2019).
melanoma (continued). "The findings that GDF6-dependent BMP signaling is observed in ~80% of patient tumors and its expression is correlated with patient survival imply that this gene and signaling pathway are potential targets for anti-melanoma therapy." (PMID 32455885, 2020). "GDF6-dependent BMP signaling was found to be critical for maintaining neural crest identity, and withdrawal of BMP signaling led to differentiation and death of melanoma cells." (PMID 32455885, 2020).
Anophthalmia (9 papers, 2010 to 2025). Absence of the globe or eyeball. "Numerous studies have reported genetic mutations in gdf6 in individuals with anophthalmia, coloboma and extraocular anomalies including cleft palate, absent ossicles, polydactyly and skeletal defects, including Klippel-Feil syndrome, hemivertebrae as well as rib and vertebral fusion." (PMID 34685584, 2021). "Growth differentiation factor 6 (GDF6) mutations may account for up to 8% of micro/anophthalmia." (PMID 21203406, 2010). "Increasing the morpholino impact/dosage resulted in more severe defects of anophthalmia, highlighting the critical role of GDF6 in ocular development." (PMID 34685584, 2021). "Previously, the GDF6 c.746C>A variant was reported in patients with KFS-like skeletal anomalies, Chiari malformation, micro- or anophthalmia, and Leber congenital amaurosis or juvenile retinitis pigmentosa, demonstrating that it can be associated with a spectrum of different phenotypes." (PMID 32737436, 2020). "Of note, anophthalmia and nanophthalmia, not previously associated with GDF6 mutations, were observed in two subjects carrying defects in this gene, expanding the spectrum of GDF6-linked ocular anomalies." (PMID 41480153, 2025).
coloboma (8 papers, 2010 to 2020). An abnormality in which a part of a structure in one or both eyes is missing. "Other zebrafish models of coloboma, such as knockdown of chd7 and gdf6, in fact, result in reduced cell proliferation in the developing eye." (PMID 25004007, 2014). "These DNA samples had been previously screened for mutations in two other coloboma-related genes, GDF3 and GDF6." (PMID 25010521, 2014).
Klippel-Feil syndrome (6 papers, 2010 to 2023). A congenital, musculoskeletal condition characterized by the fusion of at least two vertebrae of the neck. "Mutations in the prodomain of GDF6 are associated with Klippel-Feil syndrome, a congenital malformation syndrome characterized by the fusion of cervical vertebrae and variable abnormalities in multiple organs." (PMID 33147457, 2020). "Mutations in the prodomain of GDF6 are associated with several developmental abnormalities of skeleton, eye, and other organs, including Klippel-Feil syndrome." (PMID 33147457, 2020). "We demonstrate that two GDF6 prodomain mutants linked to Klippel-Feil syndrome are hyperactive in CD99-Src signaling." (PMID 33147457, 2020). "Our data also suggest that the GDF6 prodomain mutants associated with Klippel-Feil syndrome, A249E and L289P, are hyperactive in GDF6 prodomain signaling." (PMID 33147457, 2020). "Mutations in GDF6 have also been recently reported in patients with Klippel-Feil syndrome, a complex skeletal disorder characterized by congenital fusion of vertebrae within the cervical spine." (PMID 21070663, 2010). "Analysis of GDF6 in 127 individuals with Klippel-Feil syndrome identified two missense variants, p.Ala249Glu and p.Leu289Pro." (PMID 21070663, 2010). "Two recurrent GDF6 prodomain mutations in Klippel-Feil syndrome patients are A249E and L289P." (PMID 33147457, 2020). "GDF6 prodomain mutants linked to Klippel-Feil syndrome are hyperactive in GDF6-CD99-Src signaling." (PMID 33147457, 2020). "It will be important in the future to determine how hyperactive GDF6 prodomain signaling leads to abnormalities in multiple organs in Klippel-Feil syndrome." (PMID 33147457, 2020). "In contrast, the intensity of GDF6 prodomain signaling may play a critical role in the pathogenesis of Klippel-Feil syndrome." (PMID 33147457, 2020). "The interplay between hyperactive GDF6 prodomain signaling and GDF6 BMP signaling may need to be considered when dissecting the pathogenesis of Klippel-Feil syndrome." (PMID 33147457, 2020). "Of particular interest were two regions (Chr8, Max LOD = 3.04; Chr12, Max LOD = 2.09) identified within the subset of “CTD-negative” families, both of which harbor growth differentiation factors (GDF6, GDF3) implicated in the development of Klippel-Feil syndrome (KFS)." (PMID 23620759, 2013). "GDF6 has also been identified in the developing and adult human spine, and mutations in the GDF6 gene are associated with defective vertebral segmentation in Klippel-Feil syndrome, a human condition where discs in the cervical region do not develop, leading to cervical vertebrae fusion." (PMID 32992671, 2020). "In addition, a chromosomal rearrangement and several amino acid substitutions in GDF6 have been detected in patients with Klippel-Feil syndrome, a complex skeletal disorder characterized by congenital fusion of the cervical spine, and in patients with other skeletal defects." (PMID 21070663, 2010). "Interestingly, the GDF6 prodomain mutants associated with Klippel-Feil syndrome have not been reported in Ewing sarcoma, which may suggest that although the presence of GDF6 prodomain signaling is critical in Ewing sarcoma, the intensity of GDF6 prodomain signaling is not critical." (PMID 33147457, 2020).
craniosynostosis (4 papers, 2012 to 2025). Craniosynostosis is defined as the premature fusion of one or more cranial sutures leading to secondary distortion of skull shape resulting in skull deformities with a variable presentation. "Not only does this suggest potential new mechanisms for this BMP family member in regulating bone growth, it nominates GDF6 as a candidate gene harboring mutations in individuals with coronal craniosynostosis." (PMID 22693558, 2012). "The aim of this study was to gain a more thorough developmental understanding of craniosynostosis in the Gdf6−/− mouse and the underlying cause of suture fusion." (PMID 22693558, 2012). "We propose that some individuals having coronal craniosynostosis with unknown etiology may harbor mutations in GDF6." (PMID 22693558, 2012). "To determine whether a similar cell mixing was the cause of the craniosynostosis in the Gdf6−/− embryos, we visualized the suture boundary using the Wnt1-Cre and R26R transgenic lines, which together stably label derivates of the neural crest, including the frontal bone." (PMID 22693558, 2012). "The perturbation of both BMP signaling pathways, affected by GDF6 mutations, and FGF signaling pathways, affected by FGFR2 mutations, may collectively contribute to the complex phenotype observed in patients with cervical segmental insufficiency and craniosynostosis." (PMID 38561822, 2024). "This makes the craniosynostosis phenotype in the Gdf6−/− mouse particularly interesting because unlike the long bones, the cranial bones form through intramembranous ossification without a cartilage intermediate." (PMID 22693558, 2012).
Ewing sarcoma (3 papers, 2024 to 2025). A small round cell tumor that lacks morphologic, immunohistochemical, and electron microscopic evidence of neuroectodermal differentiation. "Besides its homophilic interaction, the existence of other CD99 ligands has been proposed; such as the GDF6 prodomain, which maintains Ewing sarcoma growth or the paired immunoglobulin-like receptors (PILRs), capable of binding mouse CD99." (PMID 38750588, 2024).
Hypertension (3 papers, 2021 to 2025). The presence of chronic increased pressure in the systemic arterial system. "Fibroblast Nox2 is required for AngII-induced hypertension and vascular remodeling and mediates paracrine signaling through the secretion of growth differentiation factor 6 (GDF6), which promotes vascular smooth muscle cell growth." (PMID 36139898, 2022). "In summary, this study identifies a novel paracrine-signaling mechanism involving fibroblast Nox2-dependent secretion of GDF6, which promotes vascular remodeling and hypertension in response to chronic ANG II elevation (Graphic abstract)." (PMID 33054395, 2021). "A previous study showed that GDF6 could facilitate vascular smooth muscle cell growth and that it aggravated Ang II-induced vascular remodeling and hypertension." (PMID 41462947, 2025).
prostate carcinoma (3 papers, 2023 to 2025). A carcinoma that arises from epithelial cells of the prostate gland. "GDF6, also known as BMP‐13, was the highest expressed ligand at 9% of patients with primary prostate cancer followed by BMP 2, 6, and 7 at 6% of patients, with all other ligands being expressed less than 5% of patients." (PMID 36054271, 2023).
age-related macular degeneration (2 papers, 2014 to 2016). Age-related loss of vision in the central portion of the retina (macula), secondary to retinal degeneration. "Growth differentiation factor 6 (GDF6) has been reported to be a novel disease gene for age-related macular degeneration (AMD) in Caucasians." (PMID 25416513, 2014).